MMP9 (matrix metallopeptidase 9)
Diseases named in the same sentence as MMP9 in open-access papers (continued):
Sharing a sentence is not in itself a finding about the gene and the disease.
fragile X syndrome (27 papers, 2014 to 2025). A genetic syndrome caused by mutations in the FMR1 gene which is responsible for the expression of the fragile X mental retardation 1 protein. "In a mouse model of Fragile X syndrome, loss of translational control of matrix metalloproteinase-9 (MMP9) contributed to the disease phenotype, such as delayed dendritic spine maturation." (PMID 40678520, 2025). "There is impaired development of PNNs and enhanced activity of its key regulator matrix metalloproteinase-9 (MMP-9) in Fragile X Syndrome, a common genetic cause of autism." (PMID 30123106, 2018). "Significantly, while Fmr1 genetic knockout mice, a model of fragile X syndrome, are characterized by elevated MMP9 activity and loss of perineuronal nets around parvalbumin-expressing interneurons in the auditory cortex of juvenile mice, the MMP9 deficiency restored the proper PNN formation." (PMID 34440823, 2021). "Mmp9 has also been implicated in Fragile X syndrome (FXS), which is characterized by behaviours at the extreme of the autistic spectrum." (PMID 24656144, 2014). "Several animal models of Fragile-X syndrome show increased MMP9 expression and reductions of PNNs in the amygdala, auditory cortex and hippocampus, together with impaired fear memory." (PMID 38355786, 2024). "High plasma matrix metalloproteases-9 (MMP-9) levels have been reported in Fragile X Syndrome in a limited number of animal and human studies." (PMID 36100610, 2022). "The ability of MMP-9 inhibitors to attenuate abnormalities of spine morphology and density observed in mice modeling fragile-X-syndrome (FXS) has aroused therapeutic interest in this strategy." (PMID 34439901, 2021). "Consistently, increased levels of MMP-9 have been reported in Fragile-X syndrome subjects while pharmacologically induced MMP-9 decrease leads to some degree of clinical improvement." (PMID 26839720, 2016). "We have previously shown that in the mouse model of fragile X syndrome—Fmr1 KO mice—there is an increased synaptic translation of MMP-9, which results in the higher activity of the enzyme on synapses and contributes to dendritic spine dysmorphologies." (PMID 26319558, 2016). "Genetic deletion of MMP9 rescued key features of fragile X syndrome, including dendritic spine abnormalities, exaggerated mGluR-LTD, aberrant cognitive and social behaviors as well as macroorchidism in the mouse model." (PMID 25767435, 2015). "In a controlled clinical trial, minocycline treatment was observed to lower the elevated plasma activity of MMP9 in individuals with fragile X syndrome." (PMID 25767435, 2015). "Growing evidence also suggests a role for MMP-9 in the pathophysiology of neurodevelopmental disorders including Fragile X Syndrome." (PMID 26283917, 2015). "Minocycline, a drug whose pleiotropic effects include the inhibition of MMP-9 activity, reverses filopodia transformation toward mature spines in an animal model of fragile X syndrome (Fmr1 knockout mice)." (PMID 25071472, 2014). "Similarly, in genetic disorders including Fragile X Syndrome, elevated MMP-9 correlates with PNN disruption, and genetic reduction of MMP-9 promotes PNN formation." (PMID 36339816, 2022). "Recently, we proposed a hypothesis for increased sensory hyperexcitability in Fragile X syndrome (FXS) through increased MMP-9 levels and abnormal PNN development." (PMID 30123106, 2018). "Incidentally, our study may explain the observed therapeutic effect of MMP-9 inhibition in Fragile X syndrome." (PMID 27282248, 2016). "High MMP-9 activity levels are also lowered by minocycline in fragile X syndrome patients." (PMID 25071472, 2014). "MMP-9 has been shown to be highly increased in the fragile X syndrome mouse model." (PMID 25071472, 2014). "In subjects with Fragile X Syndrome (FXS), MMP-9 is also involved in gamma asynchrony and cortical hyperexcitability of the auditory system." (PMID 38254696, 2024).
fragile X syndrome (continued). "MMP-9 translation is suppressed through its binding to FMRP, an mRNA binding protein, implicating MMP-9 in fragile X syndrome (FXS)." (PMID 26283917, 2015). "Lowering MMP-9 by minocycline has been found promising in treatment of CVD, as in treatment of the neurodevelopmental disorder Fragile X syndrome." (PMID 37430349, 2023). "The level of this enzyme is elevated in Fragile X syndrome (FXS), in which inattention, impulsivity and hyperactivity are manifested beside autism, and administration of minocycline (MMP-9 inhibitor) to mouse model of FXS results in normalization of behaviours and a decrease in anxiety." (PMID 24633733, 2015). "MMP9 activity is also important in another pathophysiological condition, Fragile X syndrome (FXS)." (PMID 25368556, 2014). "Studies reveal that MMP9 released by glia and neurons is directly responsible for PNN degradation, as evidenced by the increased densities of PNNs following genetic deletion of the MMP9 gene in Fmr1 knockout mice, a model of fragile X syndrome." (PMID 39334854, 2024). "Elevated levels of MMP-9 were reported in the amnionic fluid of subjects who went on to develop autism later in life, including a subset of individuals without Fragile-X syndrome." (PMID 26839720, 2016). "In fragile X syndrome (FXS), dysfunction of the gene product FMRP leads to MMP9 over-activation." (PMID 25182223, 2014). "The absence of FMRP results in fragile X syndrome (FXS), a condition in which MMP-9, a protein, is found to be elevated in the blood of FXS patients." (PMID 38254696, 2024).
malignant glioma (27 papers, 1999 to 2025). A grade III or grade IV glioma arising from the central nervous system. "In particular, MMP-2 and MMP-9 have been reported to be closely associated with invasion and angiogenesis in malignant gliomas." (PMID 20587068, 2010). "Finally, a recent report found that an administration of lentivirus expressing miR-451a led to an upregulation of said miRNA in malignant glioma cell lines, which caused a decrease in MMP-9, as confirmed by Western blot." (PMID 36834984, 2023). "Taken together, the JICD1/SMAD3-TWIST1-MMP2 and MMP9 axes regulate the aggressive behavior of malignant gliomas." (PMID 38092725, 2023). "A recombinant analgesic-antitumor peptide (rAGAP), a polypeptide, led to the inhibition of migration via MMP-9 inactivation in SHG44 cells (human malignant glioma cells)." (PMID 37007044, 2023). "The similar inhibitory effect of cytochalasin D on the secretion of MMP-9 was previously observed in the PMA-stimulated human malignant glioma cells, osteoclasts, and monocytes." (PMID 28740333, 2017). "The inhibition of MACC1 expression suppressed the activity of MMP-2 as well as MMP-9, leading to a decreased capacity for invasion and metastasis in malignant glioma cells." (PMID 26043756, 2015). "EFEMP1 can increase the expression and activity of MMP-2 and MMP-9 in malignant gliomas, a finding which is somewhat similar to the results of our study." (PMID 25987128, 2015). "Our results indicate that MMP-9 plays an important role in the invasion of malignant glioma cells in zebrafish embryos." (PMID 23613942, 2013). "We also measured MMP-2 and MMP-9 levels in cerebrospinal fluid (CSF) from patients with recurrent malignant gliomas." (PMID 18186943, 2008). "In our cohort of four patients with recurrent malignant gliomas, CSF MMP-9 activity progressively increased before any evidence of tumor progression on MRI." (PMID 18186943, 2008). "MMP-2 and MMP-9 are the most abundant forms of MMPs in malignant gliomas, while a 130 kDa MMP is thought to be MMP-9 complexed to other proteinases." (PMID 18186943, 2008). "Most importantly, Wong and colleagues found that increased cerebrospinal fluid (CSF) MMP-9 activity could be a biomarker of disease activity in patients with malignant gliomas, before any changes are detectable on MRI." (PMID 22995409, 2012). "Increased CSF MMP-9 activity could be a biomarker of disease activity in patients with malignant gliomas, before any changes are detectable on MRI." (PMID 18186943, 2008). "Therefore, the increasing MMP-9 activity in our cohort may reflect malignant glioma disease activity." (PMID 18186943, 2008). "Elevated MMP-9 has previously been observed in this area, and a correlation between MMP-9 expression levels and EI in malignant glioma has been reported, as well as blood-brain-barrier disruption." (PMID 41573658, 2025). "Among those, gelatinase-A (MMP-2), gelatinase-B (MMP-9), and matrix metalloproteinase-14 (MT1-MMP) are involved in different aspects of the pathophysiology of malignant gliomas." (PMID 28629170, 2017). "To examine whether our selective clones could selectively inhibit the activity of MMP14 in a cancer cell model, we performed a gelatin zymography assay with U87-malignant glioma (U87MG) cells, which naturally express high levels of MMP14, MMP9 and MMP2." (PMID 30174795, 2018). "More highly malignant glioma express increased levels of MMP-2 and MMP-9." (PMID 23613942, 2013). "In malignant gliomas, MMP-2 and MMP-9 are the most abundant forms of MMPs, while the 130 kDa MMP may represent a complex of MMP-9 and tissue inhibitor of matrix metalloproteinase-1, or a dimer of MMP-9." (PMID 18186943, 2008). "We found that the expression levels of MMP‐2, MMP‐9, ZEB1, N-cadherin, and Integrin β1 significantly diminished in the siRNA1-RACK1 and siRNA2-RACK1 groups, suggesting that siRNA-RACK1 might suppress migration and invasion of malignant glioma cells by inhibiting the EMT signaling pathway." (PMID 27763568, 2016).
respiratory failure (27 papers, 2015 to 2025). The significant impairment of gas exchange within the lungs resulting in hypoxia, hypercarbia, or both, to the extent that organ tissue perfusion is severely compromised. "In another study in COVID-19 patients from a Norwegian cohort, MMP-9 was associated with respiratory failure and low PaO2/FiO2 (P/F) ratio values." (PMID 35647937, 2022). "Similar to our findings, other studies have showed that respiratory failure, as defined by a P/F ratio, was negatively correlated with increased plasma MMP-9 and TIMP-1." (PMID 37509076, 2023). "Clinically, MMP-9 levels have shown strong correlation with respiratory failure in SARS-CoV-2–infected patients." (PMID 35076028, 2022). "MMP-9 has been reported as a potential early indicator of respiratory failure in patients with COVID-19." (PMID 33804076, 2021). "Recently, matrix metallopeptidase-9 (MMP-9) was suggested to be an indicator of respiratory failure from coronavirus disease 2019 (COVID-19) as well as useful for differentiating pulmonary from extrapulmonary TB." (PMID 33804076, 2021). "Is azithromycin (AZM) safe, and does it reduce nasal and endotracheal matrix metalloproteinase 9 (MMP-9) levels in children with respiratory syncytial virus–induced respiratory failure?" (PMID 32324238, 2020). "Moreover, MMP9 was identified as a biomarker of early respiratory failure in COVID‐19 patients because of its role in ECM remodeling." (PMID 38156385, 2023). "In addition, longitudinal increases in MMP-9 from admission to 3–5 days after hospitalization were observed in those patients who developed respiratory failure (Ueland and others 2020)." (PMID 35647937, 2022). "Among various inflammatory markers, MMP-9 was strongly associated with the P/F ratio and distinguished between patients with and without respiratory failure." (PMID 34067072, 2021). "Therefore, MMP-9 can be used as an early indicator of respiratory failure in COVID-19 patients." (PMID 34631206, 2021). "In this study, we focused on the role of MMP-9 in RSV infection based on our prior clinical observations, and did not include other critical host contributors to RSV pneumonia and respiratory failure." (PMID 26264019, 2015). "The MMP-9 level was found to be higher in all three plasma samples (days 0–2, days 3–5, and days 7–10) of the patients who developed respiratory failure compared to those of the patients who did not develop respiratory failure." (PMID 37545954, 2023). "We recently reported significantly higher MMP-9 activity in lung secretions of pediatric subjects who had respiratory failure secondary to RSV infection compared to those who had non-RSV ALI, and a positive association between early MMP-9 elevation and disease severity." (PMID 26264019, 2015).
infarction (26 papers, 2012 to 2026). A localised pathological necrosis of tissue resulting from obstruction of the blood supply usually by a thrombus, an embolus, or vascular torsion. "In contrast, MMP9 deficiency partially protects against post-infarction rupture and improves left ventricular diastolic and systolic functions." (PMID 37153746, 2023). "A previous study also demonstrated a correlation between MMP-9 and hemorrhagic transformation following infarction, while increased expression of MMP-9 has been associated with intraplaque hemorrhage in a swine model of vulnerable carotid atherosclerosis." (PMID 25667675, 2015). "In the case of the cardiac aneurysm presented in this study, the most probable cause was cardiac injury, such as infarction, and the hypoxia that followed could be responsible for the strong expression of both MMP-9 and MMP-2, as well as the remodeling of the tissue." (PMID 39682376, 2024). "MMP-9 expression levels in both the control and r-tPA groups were positively correlated with infarct volume while only r-tPA group’s MMP-9 levels were positively correlated with swelling and hemorrhage." (PMID 39273389, 2024). "Recent studies have found that MMPs are closely related to immune cells and the ablation of MMP9 decreases the infarction size in AMI." (PMID 35463752, 2022). "Though the differences were rather discreet, it is still obvious that staining of MMP-2, MMP-9, and TIMP-1 in younger wound age groups was more intense in cases with an underlying infarction compared to those with injuries of other origins." (PMID 34041592, 2021). "In conclusion, the results of the present study demonstrated that after AMI induction, MMP9−/−-tPA−/− mice had larger infarction size, lower LVEF and higher mortality than wild type mice." (PMID 32867392, 2020). "Moreover, MMP-9 was reported to be overexpressed during hypertension, atherosclerosis or infarction." (PMID 39682376, 2024). "MMP9 regulation is closely related to multiple signaling ways of cardiovascular disease, atherosclerotic plaque instability, and myocardial tissue repair after infarction." (PMID 36064568, 2022). "In contrast, other MMP family members (Mmp9 and Mmp13) were downregulated after infarction." (PMID 33063665, 2020). "Should our findings be further confirmed, MMP-9 could serve as a useful biomarker for identifying infarction in patients with vertigo or dizziness." (PMID 32982940, 2020). "Minocycline decreases MMP-9 levels, which could reduce the hemorrhagic conversion of ischemic infarcts, independently using tPA." (PMID 33520535, 2020). "Of note, MMP-9 represents the most studied MMP in relationship to CVDs, with its levels reflecting the severity of the infarction and predicting mortality in MI patients, as well as the progression of HF." (PMID 35628490, 2022). "In another study utilizing the rat MI model, the delivery of NaHS resulted not only in a reduced area of infarction and a lower level of pro-fibrotic markers, including type I collagen, type III collagen, and matrix metalloproteinase-9 (MMP-9), but also improved heart functions." (PMID 38247849, 2024).
ovarian tumor (25 papers, 2008 to 2025). "MMP-2 and MMP-9 were differentially expressed in the epithelium and the stroma of ovarian tumors associated to histological subtype, clinical stage and sexual steroid hormone receptor expression." (PMID 32718331, 2020). "The expression of MMP-2 and MMP-9 showed a significant association with the presence of androgen receptor in the epithelium of the total ovarian tumors." (PMID 32718331, 2020). "The current study evaluated the metalloproteinases MMP-2 and MMP-9 expression in epithelial cells and the surrounding stroma in ovarian tumors and the association of MMPs with the histological subtypes, the clinical stage and the presence of steroid hormone receptors." (PMID 32718331, 2020). "EGF-dependent down-regulation of E-cadherin was blocked by small interfering RNA (siRNA) specifically directed against MMP-9 and associations between EGF receptor activation, MMP-9 expression, and E-cadherin were evident in human ovarian tumors and paired peritoneal metastases." (PMID 29393911, 2018). "The aim of the current study was to evaluate the frequency of MMP-2 and MMP-9 expression in epithelial tumor cells and the surrounding stroma in ovarian tumors." (PMID 32718331, 2020). "Treatment with recombinant MMP-9 or transient expression of MMP-9 is sufficient to reduce E-cadherin levels in differentiated ovarian tumor cells." (PMID 31261642, 2019). "Taken together, the results demonstrate that pHLIP-PNA3-mediated HOTAIR inhibition reduces ovarian tumor levels of IL-6, MMP-9, and ALDH1A1, increases CDDP sensitivity and improves overall survival." (PMID 28420874, 2017). "After treatment with celecoxib or placebo, the protein expression of Ki-67, COX-2, cleaved caspase-3 and matrix metalloproteinase-9 (MMP9) in the ovarian tumors was evaluated by immunohistochemistry (IHC)." (PMID 27074576, 2016). "Previous data from our group in prostate and ovarian tumor models showed that cells overexpressing the OPNc variant induce expression of MMP2 and MMP9, highlighting the functional tissue specificity of OPN-SV." (PMID 27409830, 2016). "Our results demonstrate for the first time that oral uptake of apigenin can inhibit tumor metastasis through MMP-9 expression using the orthotopic ovarian tumor model." (PMID 22837693, 2012). "The analysis of this cohort provides evidence of the presence of MMP-2 and MMP-9 in the epithelium and stroma of ovarian tumors, showing variations in the presence of MMPs when stratified by histological subtypes, FIGO stages and expression of AR, ERα, and PR in the ovarian tumor as well." (PMID 32718331, 2020). "In addition, MMP-9 plays an important role in the cell metastasis and invasion and contributes to the ovarian tumor aggression and recurrence." (PMID 29914196, 2018). "This suggests that in the context of behavioral disorders or low social support, elevated levels of stress hormones can lead to upregulation of MMP-9, MMP-2, and VEGF expression in ovarian tumor cells via β-adrenergic receptor signaling." (PMID 38254696, 2024). "Here, we demonstrated that B7-H3 expression is also involved in ovarian tumor invasion and metastasis in vitro through upregulation of VEGF and MMP-9." (PMID 35116068, 2022). "Most of the ovarian tumor cells expressed MMP-2 and MMP-9 (pro-forms) weakly as previously observed; however, the tumor cells with partial EMT phenotypes had higher levels." (PMID 21526198, 2011). "Moreover, several invasion-related proteins such as MMP2, MMP9, and N-Cadherin have positive correlation with BCL6 in ovarian tumor cells." (PMID 30420967, 2018). "Inhibition of ovarian tumor growth in both obese and non-obese mice was significantly associated with decreased levels of COX-2, MMP9 and Ki-67 protein expression, reduction of blood vessel density and increased apoptosis." (PMID 27074576, 2016).